FTO (FTO alpha-ketoglutarate dependent dioxygenase)
Diseases named in the same sentence as FTO in open-access papers (continued):
Sharing a sentence is not in itself a finding about the gene and the disease.
leukemia (continued). "Previous studies have found the opposite results, where genetic depletion or pharmacological inhibition of FTO could suppress leukemia stem/initiating cell self-renewal and reprogram immune response." (PMID 35945194, 2022). "On the other hand, up-regulated FTO expression sensitized leukemia cells to R-2-hydroxyglutarate." (PMID 34076564, 2021). "Thus, the combination of FTO inhibitors and hypomethylating agents (HMA) is recommended for future clinical trials, in order to overcome the adaptive immune resistance induced by HMA treatment in leukemia patients with high FTO." (PMID 34235155, 2021). "In addition, R-2HG also inhibits FTO activity, thereby increasing global N6-methyladenosine (m6A) RNA modification in R-2HG-sensitive leukemia cells." (PMID 33897884, 2021). "Moreover, a recent study found that R-2HG also suppresses glycolysis in leukemia cells by abrogating FTO/m6A/YTHDF2-mediated upregulation of two critical glycolytic genes phosphofructokinase platelet (PFKP) and lactate dehydrogenase B (LDHB)." (PMID 34485297, 2021). "FTO plays an oncogenic role through facilitating cell proliferation and leukemogenesis, and inhibiting all-trans-retinoic acid-mediated differentiation of leukemia cells." (PMID 34149801, 2021). "Due to the downregulation of FTO, leukemia cells were more sensitive to T cell cytotoxicity and immune evasion could be avoided." (PMID 34650549, 2021). "We anticipate that this study may provide insight into a promising strategy for target FTO/m6A-based epitranscriptome and highlights the clinical potential of Saikosaponin for leukemia therapy." (PMID 33897884, 2021). "FTO is highly expressed in acute myeloid leukemia, which could enhance the occurrence of leukemia, and inhibit the transretinoic acid-mediated differentiation of leukemia cells." (PMID 33816306, 2021). "Targeting FTO could make leukemia cells more sensitive to T cell toxicity and overcome immune evasion induced by hypo-methylation agents, suggesting the potential value of targeting FTO in anticancer treatment." (PMID 34956201, 2021). "For leukemia cells, FTO inhibitors can not only block the signal axis of FTO/m6A/MYC/CEBPA and inhibit the self-renewal of cancer stem cells, but also suppress the expression of immune checkpoint LILRB4 and immune evasion thus enhancing the cytotoxicity of T cells." (PMID 33598423, 2020). "IDH mutations can weaken FTO activity in about 20% of patients with AML; they improve m6A modification without affecting FTO expression, which provides a novel target for the clinical treatment of leukaemia." (PMID 33029866, 2020). "In addition, some researchers have focused on targeted cancer therapies related to m6A, such as treatment with R-2HG to increase m6A mRNA modification in R-2HG-sensitive leukemia cells by inhibiting FTO activity, thus generating antileukemia effects." (PMID 32398132, 2020). "Knockdown of FTO remarkably sensitizes resistant leukemia cells to TKI treatments." (PMID 32111216, 2020). "While FTO has been shown to play an important role in leukemia, it is possible that additional RMPs such as HENMT1, which is drastically dysregulated in this cancer type, might constitute a better drug target to inhibit leukemogenesis." (PMID 32375858, 2020). "The overexpression of FTO in leukemia cells can promote its expression by catalyzing the demethylation of cell proliferation-related genes such as m6A of MERTL and BCL-2 mRNA and affecting the generation of resistance phenotypes in the treatment with tyrosine kinase inhibitors (TKI)." (PMID 33304380, 2020). "A recent study showed that combination of FTO inhibitor and nilotinib can restrain the growth of leukemia and increase the sensitivity of leukemia cells to tyrosine kinase inhibitors, highlighting the potential therapeutic value of targeting m6A regulators in drug-resistant cancers." (PMID 32911345, 2020).
leukemia (continued). "Inactivation of FTO in leukemia induced sensitivity of resistance cells to tyrosine kinase inhibitor, indicating that the FTO-m6A axis may serve as novel potential therapeutic target in human cancers." (PMID 30922314, 2019). "Indeed, the oncogenic role of FTO has been reported in leukemia and glioblastoma (GBM), where FTO is highly expressed." (PMID 30105001, 2018). "Therefore, R-2HG displays anti-leukemia activity by suppressing FTO/m6A/MYC/CEBPA signaling, as well as relevant pathways." (PMID 30149601, 2018). "Further, the FTO/m6A axis could serve as a biomarker to predict response of the leukemia patients to the TKI treatment." (PMID 30297871, 2018). "Therefore, inhibiting FTO through such small molecules may offer a promising approach in combating leukemia." (PMID 38711100, 2024). "Notably, in leukemia, inhibition or reduction of FTO expression blocks leukocyte immunoglobulin-like receptor B4, an immune checkpoint gene expression, inhibits the self-renewal ability of stem cells, while enhancing leukemia sensitivity to drugs and preventing the development of immune evasion." (PMID 39033180, 2024). "Interestingly, saikosaponin-d (SsD), extracted from Radix Bupleuri, restored the sensitivity of resistant leukemia cells to nilotinib by reversing FTO-mediated m6A hypomethylation, which may provide a new approach for the treatment of acute myeloid leukemia." (PMID 37264402, 2023). "However, FTO is engaged in the tumorigenesis and development of leukemia as an oncogene." (PMID 35999621, 2022). "Moreover, FTO is responsible for TKI resistance in leukemia cells, suggesting that targeting FTO may reverse TKI resistance." (PMID 35720276, 2022). "Importantly, SsD also overcame FTO/m6A-mediated leukemia resistance to tyrosine kinase inhibitors." (PMID 33897884, 2021). "Additionally, a report demonstrated that pharmacological function of FTO inhibitor could slow down the self-renewal of leukemia stem cells." (PMID 33744868, 2021). "It is difficult to say whether FTO plays an oncogenic role in leukemia or is related to snRNA." (PMID 33162550, 2020). "Notably, FTO has been been found to be involved in leukemia, DNA damage repair, and heat stress." (PMID 31992337, 2020). "Thus, FTO could be suppressed by R-2HG in sensitive leukemia cells to elevate global m6A RNA modification, which destabilizes the MYC/CEBPA transcripts and reduces their expression." (PMID 31921664, 2019). "Importantly, such FTO deregulation is required for leukemia cells to establish TKI resistance." (PMID 30297871, 2018). "We also analyzed the fold changes of m6Am, Am, Cm, Gm, and Um-initiated mRNAs in leukemia cells, and found that m6Am-initiated mRNAs showed an even smaller fold change in expression than the other four groups of mRNAs upon R-2HG treatment or FTO overexpression." (PMID 29686311, 2018). "Specifically, R-2HG inhibited FTO activity, thereby increasing global m6A RNA modification and reducing the stability of MYC/CEBPA transcripts in R-2HG-sensitive leukemia cells, showing antitumor activity." (PMID 41362736, 2026). "Conversely, uninhibited FTO reduced RARA and ASB2 protein expression and suppressed all-trans retinoic acid (ATRA)-induced leukemia cell differentiation." (PMID 40823087, 2025). "In the study of acute myeloid leukemia (AML), it was found that FTO can upregulate proteins such as PML-RARA and NPM1 to promote the occurrence and development of leukemia." (PMID 39820532, 2025). "Current m6A demethylase drugs, such as FTO inhibitors like FB23, rhein, and 44/ZLD115, show potential, particularly 44/ZLD115's potent anti‐leukemia effects." (PMID 40916616, 2025).
leukemia (continued). "Consistently, down-regulation of Elk3 was also found in primary murine Fto−/− leukemia cells, suggesting that the activation of ELK3 expression by FTO is an evolutionarily conserved regulatory mechanism in human and mouse." (PMID 40435251, 2025). "In a study where R-2HG was shown to attenuate aerobic glycolysis in leukemia by targeting the FTO/m6A/PFKP/LDHB axis, it was found that PFKP promotes glycolysis and exerts an oncogenic role in leukemia." (PMID 39820532, 2025). "FTO inhibitor 44/ZLD115 upregulates RARA and downregulates MyC in leukemia cells, inducing apoptosis." (PMID 39802639, 2025). "The FTO inhibitors R-2HG and FB23-2 can inhibit the growth of leukemia cells and slow the progression of leukemia; FB23-2 is more effective and can significantly inhibit acute myeloid leukemia progression in xenograft mice." (PMID 38937660, 2024). "The use of small-molecule inhibitors targeting FTO affected the expression levels of downstream genes such as MYC, CEBPA, RARA, and ASB2, thereby exerting anti-leukaemia effects." (PMID 39641872, 2024). "It has also been established that D-2HG exerts anti-leukemia effects by regulating the FTO/m6A/MYC/CEBPA pathway and FTO/m6A/PFKP/LDHB axis." (PMID 38982076, 2024). "screened two highly effective and selective FTO inhibitors, CS1 and CS2, showing a better effect in suppressing leukemia cell activity than FB23-2 and MO-I-500 (two other previously reported FTO inhibitors)." (PMID 36960074, 2023). "Meanwhile, c-Myc was regulated by FTO via m6A modification in HCC, which was similarity in leukemia, colorectal cancer, gastric cancer, glioma and lung adenocarcinoma." (PMID 37840133, 2023). "In terms of the mechanism, FTO reduces expression of tumor suppressors RARA and ASB2 by impairing their mRNA stability, and thus facilitates the occurrence of leukemia." (PMID 35999621, 2022). "FTO regulates the translation of PFKP, LDHB, ASB2, and RARA mRNA in a m6A-dependent manner to promote the occurrence of leukemia." (PMID 35945641, 2022). "In leukemia, the resistance to tyrosine kinase inhibitor (TKI) is dependent on over-expression of FTO." (PMID 35022030, 2022). "FTO alpha-ketoglutarate-dependent dioxygenase (FTO) is an m6A demethylase, and it can be induced to express by TKIs in leukemia." (PMID 36115852, 2022). "FTO and ALKBH5, m6A demethylases, are abnormally expressed in AML and promote tumorigenesis and self-renewal of leukemia stem cells through m6A-dependent regulation of their target mRNAs13–15." (PMID 35217832, 2022). "In leukemia, the use of CS1 and CS2 targeting FTO increases the sensitivity of AML cells to T cell toxicity and overcomes HMA-induced immune escape, thereby achieving therapeutic effects." (PMID 35590394, 2022). "In leukemia, some studies displayed a negative correlation between m6A and apoptosis—Bcl-2 overexpression evoked by FTO and ALKBH5 upregulation fights against apoptosis, resulting in resistance of leukemia cells to tyrosine kinase inhibitors (TKIs)." (PMID 35090469, 2022). "FTO promotes the self-renewal of leukemia stem cells (LSCs) and TIE, which can be reversed by small-molecule FTO inhibitors (FTOis)." (PMID 36071523, 2022). "Small-molecule inhibitors of METTL3, FTO, ALKBH5 have recently been identified and have exhibited considerable anti-leukemia effects both in vitro and in mouse models." (PMID 35999621, 2022). "R-2HG can block the post-transcriptional upregulation of PFKP and LDHB mediated by FTO/m6A, thus attenuating aerobic glycolysis in sensitive(IDH-wildtype) leukemic cells and inhibiting the occurrence of leukemia." (PMID 35590394, 2022). "Altogether, these results further demonstrated that FTO and its downstream targets (e.g., MYC, RARA) are the major effectors of SsD in FTO overexpressed leukemia cells." (PMID 33897884, 2021). "Targeting FTO decreases leukemic CSC self-renewal and sensitizes leukemia cells to T cell cytotoxicity." (PMID 33741917, 2021).
leukemia (continued). "For instance, increased expression of several m6A modifiers such as METTL3, FTO, and ALKBH5 have been observed in leukemia cells (discussed in the following)." (PMID 34485297, 2021). "FTO is highly expressed in leukemia cells from different subtypes of AML, and especially in leukemia stem cells." (PMID 34485297, 2021). "By regulating the expression of the leukemia-related oncogenes ASB2 and RARA, FTO overexpression can downregulate the total level of m6A, promote cell growth and colony formation in vitro, and promote the occurrence of leukemia in vivo." (PMID 34381710, 2021). "FTO upregulation and m6A hypomethylation increased TKI tolerance in leukemia treatment, through enhancing the mRNA stability of proliferation/survival transcripts containing m6A modification." (PMID 34345203, 2021). "Intriguingly, reasons of m6A dysregulation in CSCs are different among various types of cancer, considering the roles of FTO, ALKBH5, and METTL3 in glioblastoma stem cells and of METTL14 and FTO in leukemia stem cells." (PMID 32676121, 2020). "Most recently, it has been reported that FTO plays a carcinogenic role through the FTO/m6A/MYC/CEBPA signaling pathway in IDH mutant cancers, such as glioma and leukemia." (PMID 32211315, 2020). "Conversely, levels of the m6A demethylase “erasers,” including FTO and ALKBH5, were increased in kidney cancer and leukemia but decreased in BC, brain, CNS and ovarian cancer." (PMID 30953473, 2019). "No known FTO paralog exists, and FTO depletion on its own was reported to impact leukemia cell growth." (PMID 41279954, 2025). "We also evaluated HEK293T cells, which are not leukemia-derived, and tested both wild-type and FTO knockout (KO) lines." (PMID 41279954, 2025). "In addition, combined blockade of PD-L1 checkpoint and expression of YTHDF1, FTO, and METTL3/14 was able to improve the significant effect in the treatment of CRC and leukemia." (PMID 39033180, 2024). "In addition, the FTO/m6A/PFKP/LDHB axis is targeted by R-2-hydroxyglutarate, resulting in the suppression of aerobic glycolysis in leukemia." (PMID 37858219, 2023). "R-2-hydroxyglutarate, a FTO inhibitor, could suppress the expression of FTO/PFKP/LDHB and impair aerobic glycolysis in leukemia." (PMID 35692393, 2022). "In addition, targeting FTO decreased the expression of immune checkpoints, such as PD-L1, PD-L2, and LILRB, to reverse immune evasion of leukemia cells, highlighting the potential of FTO inhibitors for cancer therapy." (PMID 35859892, 2022). "Moreover, through targeting the FTO/MYC/CEBPA axis, R-2HG inhibited the proliferation of leukemia cells." (PMID 35186927, 2022). "Similarly, targeted inhibition of FTO and METTL3/14 combined with anti-PD-1 based immune checkpoint blockade therapy has been used for leukemia and colorectal cancer." (PMID 35794625, 2022). "Moreover, it increases m6A modification of RNA by inhibiting FTO activity, destabilizing CEBPA/MYC transcripts in leukemia cells." (PMID 35186927, 2022). "Likewise, targeting FTO/MYC/CEBPA signaling, R-2HG displays an intrinsic and broad anti-tumor activity in leukemia." (PMID 36035161, 2022). "FTO and ALKBH5 are also involved in the occurrence and promotion of leukemia." (PMID 35945641, 2022). "Interestingly, the results from our experiments revealed that NPM1-mA reduces the global m6A abundance by upregulating FTO expression, suggesting the possible link between NPM1-mA and the aberrant m6A modification in leukemia." (PMID 35211409, 2022). "FTO knockout or inhibition can significantly inhibit the self-renewal of leukemia stem cells, thus hindering the occurrence and development of AML; conversely, high expression of FTO promotes the growth of leukemia cells and accelerates leukemogenesis." (PMID 34485297, 2021). "In addition, combined treatment with FTO inhibitors and nilotinib eradicates the TKI resistance phenotype and impairs leukemia cell propagation both in vitro and in vivo." (PMID 34001273, 2021).
leukemia (continued). "FTO reduces the concentration of m6A in mRNA transcripts, regulates the expression of targets such as ASB2 and RARA, and inhibits the differentiation of AML cells induced by ATRA to promote the development of leukemia." (PMID 34858499, 2021). "Similarly, two small-molecule FTO inhibitors (CS1 and CS2) have been shown to significantly attenuate the self-renewal and reprogram immune response of leukemia stem/starter cells by suppressing the expression of immune checkpoint genes." (PMID 34573357, 2021). "The FTO activity inhibited by R-2-hydroxyglutaric acid (R-2HG) increases the level of m6A modification and promotes the degradation of MYC and CEBPA through an YTHDF2-dependent pathway, resulting in inhibited growth of leukemia cells." (PMID 33926508, 2021). "have revealed that deletion of FTO, an m6A regulatory protein, could inhibit the expression of LILRB4, thus dramatically attenuating the reprogram immune response of the leukemia stem cell." (PMID 34650549, 2021). "Importantly, combined treatment with an FTO inhibitor and nilotinib works synergistically to overcome the TKI resistance phenotype and suppress leukemia growth in both in vitro and in vivo models." (PMID 32111216, 2020). "In addition, FTO erases m6A modification of tumor suppressor genes MYC/CEBPA, which contributes to the tumor formation of leukemia." (PMID 31722709, 2019). "Furthermore, through negatively regulating a set of critical genes (e.g., ASB2 and RARA) in AML as RNA m6A demethylase, FTO plays an oncogenic role and inhibits all-trans-retinoic acid (ATRA)-mediated differentiation of leukemia cells." (PMID 30149601, 2018). "Thus, an FTO paralog is unlikely to explain why FTO is not detected as a leukemia dependency gene in DepMap." (PMID 41279954, 2025). "Yet, it is not well understood whether and how the FTO/m6A axis empowers leukemia cells to survive prolonged drug exposure through non-protein-coding genes." (PMID 41203598, 2025). "Additionally, FTO can enhance the stability of MYC and CEBPA mRNA, thereby promoting cell proliferation, and METTL14 and YTHDF2 promote the self-renewal of leukaemia stem cells (LSCs)/leukaemia initiating cells (LICs), while ALKBH5K promotes LSC proliferation and induces apoptosis." (PMID 39641872, 2024). "FTO downregulates m6A levels, modulates the expression of Ankyrin Repeat and SOCS Box Containing 2 (ASB2) and Retinoic Acid Receptor Alpha (RARA), enhances gene-mediated cell transformation and leukemia onset, and inhibits acute myeloid leukemia (AML) cell differentiation." (PMID 38711100, 2024). "Also, FTO inhibitors (FB23 and FB23-2) provide a therapeutic strategy for treating leukemia." (PMID 35186927, 2022). "Likewise, overexpression of FTO could promote BCL-2 expression, thereby reducing the sensitivity of leukemia cells to tyrosine kinase inhibitors (TKIs)." (PMID 35843942, 2022). "Thus, the combination of FTO inhibitors and TKIs could exhibit more favorable efficacy than TKI monotherapy for treating leukemia in mouse model." (PMID 35999621, 2022). "Scholars have reported that R-2-hydroxyglutarate (R-2HG) abates FTO/m6A/YTHDF2-mediated upregulation of phosphofructokinase platelet (PFKP) and lactate dehydrogenase B (LDHB) which suppress aerobic glycolysis and exert an anti-tumor effect in R-2HG-sensitive leukemia cells." (PMID 36035161, 2022). "Moreover, increased T-cell cytotoxicity and reduced self-renewal abilities of AML cells were noted in the treated mice, suggesting that CS1 and CS2 are potent inhibitors of FTO and can be developed as potential therapeutics against LSC by increasing anti-leukaemia T-cell activity." (PMID 34207299, 2021). "R-2-Hydroxyglutarate (R-2HG) directly binds to the FTO (which participates in the m6A process) and inhibits its activity, thereby reducing the m6A modification and stability of c-MYC and CEBPA in the 5′-UTR and coding regions, leading to apoptosis of leukemia cells." (PMID 34858499, 2021).